ENSG00000287704 (novel transcript)
Gene: Long non-coding RNA gene on chromosome 15 (46,404,022 to 46,805,232, forward strand). Ensembl gene ENSG00000287704.
Gene Ontology:
Molecular function: U4 snRNA binding
Biological process: formation of quadruple SL/U4/U5/U6 snRNP; spliceosomal tri-snRNP complex assembly
Cellular component: U4/U6 x U5 tri-snRNP complex; U6 snRNP